EOLA1-DT (EOLA1 divergent transcript)
Synonyms: lnc-CPLC; LINC00893
Gene: Long non-coding RNA gene on chromosome X (149,527,591 to 149,540,959, reverse strand). Ensembl gene ENSG00000241769.
Diseases named in the same sentence as EOLA1-DT in open-access papers:
EOLA1-DT is named in the same sentence as 8 diseases in open-access papers, as found by Europe PMC text mining. Sharing a sentence is not in itself a finding about the gene and the disease.
EOLA1-DT shares sentences with these, for which no sentence is quoted: tumor (4 papers); asthma (1); cancer (1); colon cancer (1); ovarian carcinoma (1); prostate carcinoma (1); signet ring cell carcinoma (1); thyroid cancer (1).